HK3 (hexokinase 3)
Diseases named in the same sentence as HK3 in open-access papers (continued):
Sharing a sentence is not in itself a finding about the gene and the disease.
cancer (22 papers, 2002 to 2025). A tumor composed of atypical neoplastic, often pleomorphic cells that invade other tissues. "HK3 encodes hexokinase 3, an important isoform of hexokinase involved in the glycolytic process and is recognized as a significant biomarker in various cancers." (PMID 40177399, 2025). "The inactivation of HK3 notably affects the activation of cancer cells glycolysis, and then activates the downstream signaling pathways, such as apoptosis and endoplasmic reticulum stress." (PMID 37434985, 2023). "The latest research about the functions of HK3 in normal and cancer cells has uncovered previously unanticipated roles of this protein." (PMID 37109475, 2023). "In this study, from enrichment analysis of GSEA, the HK3 gene was notably enriched in cancer pathways, cellular communication factor, PI3K-Akt Pathway, and virus response." (PMID 37434985, 2023). "In this study, we performed a comprehensive analysis of the role of HK3 in GBM using The Cancer Genome Atlas (TCGA), Chinese Glioma Genome Atlas (CGGA), Tumor Immune Single Cell Hub (TISCH), and Human Protein Atlas (HPA) databases." (PMID 36712881, 2022). "We first explored HK3 expression and its prognostic value at the pan-cancer level using the TCGA database." (PMID 36712881, 2022). "The advantage of this study is that we first assessed the prognostic implications of the differential expression levels of HK3 in ccRCC and pan-cancers based on large-scale population cohorts." (PMID 34239350, 2021). "In this study, significantly prognostic implications of HK3 has been identified in ccRCC based on multiply cohorts (n>1,500) and in many cancers." (PMID 34239350, 2021). "After proving that HK3 is related to the immune environment of ccRCC, we further studied the role of HK3 in pan-cancer." (PMID 34239350, 2021). "Compared with the three hexokinase isozymes, HK1, HK2, and HK4, the role and mechanism of action of HK3 in cancer is less reported." (PMID 33980323, 2021). "The genes with CNV amplifications exhibited a significantly higher expression in cancer tissues than in normal controls (e.g., HK3 and ENO2), while the genes with CNV deletions exhibited significantly lower expression (e.g., ALDOB and PSAT1)." (PMID 33564363, 2021). "LPS activates inflammasomes in cancer cells through NF-κB and promotes metastasis through glycolysis enhanced by the NF-κB/Snail/HK3 signaling pathway in CRC." (PMID 33980323, 2021). "For further evaluation of HK3 expression in human cancers, HK3 expression was assessed using RNA‐seq data from multiple malignancies in the TCGA database." (PMID 32508023, 2020). "This family harbours several genes aberrantly expressed in various cancers as well as established (PSA/hK3, hK2) and potential (hK6, hK10) cancer markers." (PMID 12439719, 2002). "Increasing research have indicated that HK3 is an important biomarker in various cancers." (PMID 37106446, 2023). "The results showed dysregulation of HK3 expression in 14 types of human cancers." (PMID 36712881, 2022). "HK3 expression was explored at the pan-cancer level using TIMER2.0." (PMID 36712881, 2022). "TISCH analysis showed that HK3 was predominantly expressed in macrophages in most cancers." (PMID 36712881, 2022). "At the same time, we investigate prognostic role of HK3 in various cancers." (PMID 34239350, 2021). "As a cancer-related gene, HK3 plays a vital role in the TIME, so it may be feasible to consider it a TAA for GBM." (PMID 34527020, 2021). "Among them AAAS, HK3, and ADPGK the expression of three genes was obviously raised in cancer samples and was significantly correlated with prognosis." (PMID 41035662, 2025). "There are four subtypes of HK, namely HK1, HK2, HK3 and HK4, among which HK1 and HK2 play a role as drivers of cancer cell glycolysis." (PMID 39895802, 2025). "Among all four isoforms of HK (HK1, HK2, HK3, and HK4), HK2 was found to be highly expressed in patients with carcinomas and considered the most efficient isoform in aerobic glycolysis." (PMID 34368116, 2021).
cancer (continued). "More specifically, HK3 displayed predominantly negative correlations across most cancer types, suggesting a widespread involvement of these enzymes in metabolic pathways influenced by PEBP1/STK11 levels." (PMID 40806276, 2025). "Importantly, the HK3 and ADCK3 genes were not only highly expressed in HCC but also correlated with PI3K/Akt Pathway and cancer pathways." (PMID 37434985, 2023). "As for HK3, its role in cell viability was not significant, but more investigations are deserved considering its emerging roles in other cancers." (PMID 36494582, 2023). "In conclusion, ARPC1B and HK3 were considered the possible TAAs of GBM, and mRNA cancer vaccine therapy may be more beneficial for patients in IS2." (PMID 34527020, 2021). "This study found that HK3 stimulates the infiltration of monocytes/macrophages presenting surface markers, regulates the key molecules PD-1 and CTLA-4 of exhaustive T cells, and affects the immune escape process of cancers." (PMID 34239350, 2021). "No other studies have described the role of HK3 in human cancers." (PMID 29504907, 2018). "Furthermore, differences were observed in the expression of several non-canonical and/or embryonic isoforms (HK3, HKDC1, ALDA, GADPH-S, PGK2, and PKM) between patients and controls, as well as in the expression of isoforms considered hallmarks of cancer, such as HK2." (PMID 41009047, 2025).
bacterial infection (2 papers, 2008 to 2022).
HK3 also shares sentences with these, for which no sentence is quoted: colon cancer (3 papers); COVID-19 (3); melanoma (3); Obesity (2); skin cutaneous melanoma (2); acute lymphoblastic leukemia (1); astrocytomas (1); autoimmune thyroid disease (1); bone metastasis (1); cervical squamous cell carcinoma (1); endocervical adenocarcinoma (1); head and neck squamous cell carcinoma (1); hearing (1); Hepatic steatosis (1); infection (1); influenza (1); kidney chromophobe (1); ovarian serous cystadenocarcinoma (1); ovarian tumor (1); pancreatic adenocarcinoma (1); premature ovarian failure (1); testicular germ cell tumor (1); thymoma (1); type 2 diabetes mellitus (1); uveal melanoma (1).